CD4 (CD4 molecule)
Diseases named in the same sentence as CD4 in open-access papers (continued):
Sharing a sentence is not in itself a finding about the gene and the disease.
influenza (continued). "Currently, most available peptide pools for influenza are optimised for CD8, rather than CD4 cells." (PMID 28146323, 2017). "Despite this, CD4 and CD8 T-cell expansion in response to influenza virus was comparable in CD30+/+ and CD30−/− littermates, with no discernable role for the pathway in the outcome of influenza infection." (PMID 28993768, 2017). "In a former report, influenza vaccine administration did not influence the number of total CD4+CD25+ T cells, and it was supposed that the response to vaccine depends on the activation of different subsets of CD4+CD25+ T cells." (PMID 28511719, 2017). "However, it has been shown that influenza-specific IgG responses, as measured by antibody levels, are not impaired in HIV-infected individuals following vaccination, irrespective of CD4 count." (PMID 22715399, 2012). "For example, net gelatinase activity in BALF and numbers of CD4+ and CD8+ lymphocytes in LNs were reduced in mice that were smoke exposed before influenza infection, in comparison to mice that were not smoke exposed before influenza infection." (PMID 18627612, 2008). "On IL-4 stimulation, we saw an upregulation of Ki-67 in human CD4 T cells but not NHP cells, much akin to IFNγ stimulation, and high expression of pSTAT3 in the natural killer of IL-4-stimulated blood cells, but not in PBMCs from humans challenged with influenza." (PMID 36624212, 2023). "The lack of conserved and common CD4+ T-cell epitopes within HA of H7N9 could negatively affect the efficiency of inactivated vaccines; given the synergistic role of antibody and T-cell responses against influenza." (PMID 24609014, 2014). "Besides the absence of any increase in influenza-specific CD8 cells after IM vaccination, we also observed significant differences in the distribution of single (SP), double (DP) and triple (TP) cytokine producing CD4 cells on D28 according to the vaccination route." (PMID 20520820, 2010).
lupus (804 papers, 2005 to 2026). "In systemic lupus erythematosus, the CD4/CD8 ratio is associated as a good indicator of therapeutic efficacy." (PMID 40981339, 2025). "Iron deficiency reduces the levels of TFR1 and FTH1 in splenic CD4+ T cells, supporting Treg expansion and protecting Tregs from apoptosis via limiting ROS production in pristane‐induced lupus." (PMID 40045458, 2025). "Related findings indicate the pathogenic role of unusual CD4+B220+ T cells in lupus in MRL/lpr mice based on their IL-17–producing capacity and conventional stimulatory function." (PMID 40243626, 2025). "X-linked miRNAs, notably in active lupus, show significant sex-specific expression in CD4 + T cells, influenced by epigenetic mechanisms like demethylation, though comprehensive understanding of XCI-escaping miRNAs requires further investigation." (PMID 39731171, 2024). "Recent studies have shown that miR-21 overexpression in CD4+T cells promote iron accumulation by inhibiting 3-hydroxybutyrate dehydrogenase 2 (BDH2) in lupus-susceptible mice." (PMID 39726588, 2024). "Downregulation of Cbl-b in CD4+ T cells has recently been reported in systemic lupus erythematosus (SLE) patients, and Cbl-b-deficient SLE patients exhibited T follicular helper (Tfh) cell hyper-responses." (PMID 39768300, 2024). "In another study, high XIST expression has been found to be associated with the CD4-positive T cell level in systemic lupus erythematosus patients." (PMID 38265097, 2024). "Previous studies have indicated that m5C modification is associated with the development of systemic lupus erythematosus through its influence on CD4+ T cells involved in immune responses." (PMID 38271969, 2024). "In contrast, in the IVDD group, key pathways highlighted genes that were upregulated in myeloid cells compared to B cells and CD4+ T cells, as well as upregulated genes in lupus-associated myeloid cells compared to lupus-associated B cells and CD4+ T cells." (PMID 39769264, 2024). "Systemic Lupus Erythematosus (SLE) etiopathogenesis highlights the contributions of overproduction of CD4+ T cells and loss of immune tolerance." (PMID 37875396, 2023). "It has been reported that PP2A overexpression is linked with enhanced IL-17 production by CD4+ T cells in patients with systemic lupus erythematosus (SLE)." (PMID 37234102, 2023). "Here, we show that Trex1 deficiency-induced endogenous DNA accumulation in CD4+ T cells greatly promoted their induction of autoimmune inflammation in a lupus-like mouse model." (PMID 39872301, 2023). "The downregulation of A20 in CD4 + T cells from systemic lupus erythematosus was closely associated with demethylation of histone H3K4, which led to a decreased amount of H3K4me3 in the promoter of the A20 gene." (PMID 36788604, 2023). "The aberrant DNA methylation in CD4+ T cells was also found to be associated with systemic lupus erythematosus (SLE) and systemic sclerosis." (PMID 37228600, 2023). "In summary, our study provides the direct evidence on the involvement of pathogenic CD4+ T cells in IgG production in pristane-induced lupus-like mice." (PMID 35095344, 2022). "CD4+T cells in lupus patients and lupus-susceptible mice depend on enhanced glycolysis for rapid ATP production to meet their glucose requirements." (PMID 36203617, 2022). "All these murine findings confirmed that loss of CD4+ T‐cell‐intrinsic Aim2 ameliorated lupus symptoms by regulating the TFH response." (PMID 35343082, 2022). "All these data suggested Aim2 deficiency in CD4+ T cells ameliorated lupus features in pristane‐induced lupus model." (PMID 35343082, 2022). "The Sle1c2 sublocus is another lupus susceptibility gene segment, which contributes to an elevated CD4+ T cell activation, a robust age-dependent expansion of IFN-γ-expressing Th1 cells, and a decrease in Treg counts." (PMID 36389689, 2022). "ETS1 and FLI1, susceptibility genes associated with systemic lupus erythematosus, were differentially expressed in CD4+ and CD8+ effector cells in G1 and G3." (PMID 36703979, 2022).
lupus (continued). "It has been reported that lupus-susceptible mice carry a great quantity of activated T cells, and CD4+ T cells in SLE have signal defects." (PMID 36467552, 2022). "E4BP4 deficiency in CD4+ T cells in lupus resulted in overexpression of BCL-6, which promoted Tfh cell differentiation and function and exacerbated pristane-induced lupus-like diseases." (PMID 35637283, 2022). "The transcriptomic or translational profiles of lupus CD4+ T cells can lead to a better understanding of pathogenic mechanisms of SLE, and aid in potential therapeutic targets identification in an unbiased manner." (PMID 36046235, 2022). "The CD4+CD25-FoxP3+ T-cell population has been observed in inflammatory diseases such as systemic lupus erythematosus previously and was associated with rather adverse immune outcomes." (PMID 35883769, 2022). "The frequency of CD4+ CD28null T-cells is correlated with endothelial dysfunction in hypertensive patients and a cardiovascular risk in systemic lupus erythematosus; their expression of CXCR4 suggests a BM homing property." (PMID 34680058, 2021). "The core fucosylation of CD4+ T cells is significantly increased in systemic lupus erythematosus patients, and loss of FUT8 reduced CD4+ T cell activation." (PMID 34948129, 2021). "The lupus susceptibility allele of Esrrg corresponds to a lower expression that correlates with CD4+ T cell activation and defective Tregs." (PMID 34156979, 2021). "An overexpression of ACE2 mRNA in CD4+T cells has also been described in patients with systemic lupus erythematosus, a disease that is associated with interferon induction." (PMID 34325716, 2021). "The levels of IL-17 and IFN- γ, the pro-inflammatory cytokines that are implicated with the pathogenesis of lupus, were decreased in culture supernatant of PD-L1 positive MDSCs and CD4+T cells." (PMID 33986739, 2021). "IL-6-deficient mice exhibit resistance to lymphocyte-derived DNA-induced lupus, which causes CD4+ T cell activation, anti-dsDNA autoantibody titers, proteinuria, and glomerulonephritis." (PMID 34394075, 2021). "In the cGVHD lupus model, the key cellular mechanism that results in the loss of B-cell tolerance is the interaction of donor CD4+ T cells with MHC class II on the host B-cell surface." (PMID 34504495, 2021). "PCG alleviated nephritis in lupus-prone mice by regulating serum pro-inflammatory and anti-inflammatory cytokines, rebalancing CD4+ T cell subsets, and diminishing LN-pathogenic autoantibodies." (PMID 32674502, 2020). "In conclusion, we presented that the deletion of Mir223 exacerbated the lupus phenotypes associated with increased population of S1PR1+CD4+ T cells and their enhanced infiltration in inflamed kidney tissues." (PMID 33574820, 2020). "Recently, we also identified novel aberrant mRNA modification, 5-methylcytidine (m5C), linked to critical immune pathways in lupus CD4+ T cells." (PMID 32984334, 2020). "In a six-month prospective study of 20 lupus patients with vitamin D deficiency, the adequate supplementation of vitamin D (cholecalciferol) led to reductions in the frequencies of Th1 and Th17 CD4+ T cells, while the frequency of the Treg cells increased." (PMID 30103428, 2018). "Our previous observation of lupus-associated NKG2D+CD4 T cell population expansions was made in patients with the juvenile-onset form of this disease." (PMID 28944101, 2017). "Since exacerbation of the lupus syndrome in the B7-H4-deficient BMDCs-ALD-DNA induced model can be abolished by CD4+ T cell depletion in vivo, thus this suggests that the B7-H4 signal mainly affects CD4+ T cell function to affect lupus disease manifestations." (PMID 29321778, 2017).
lupus (continued). "In T cell-specific SOCS1-conditional knockout mice, SOCS1-deficient CD4+ naïve T cells mostly differentiated into Th1 cells, and Th17 differentiation was strongly suppressed; these mice eventually developed a lupus-like autoimmune disease." (PMID 29085365, 2017). "HLA-DR expression by CD8+ T lymphocytes or by CD4+ lymphocytes appeared to be associated with the occurrence of a lupus flare." (PMID 29065901, 2017). "Although the murine Tnfrsf21 gene (on chromosome 17) is not in murine SLE-associated loci, the unique characteristics of the lupus CD4+ T cell populations emphasize the importance of DR6 functions in the regulation of CD4+ T cells in lupus-prone mice." (PMID 28045014, 2017). "Wu, H.Y.; Quintana, F.J.; Weiner, H.L. Nasal anti-CD3 antibody ameliorates lupus by inducing an IL-10-secreting CD4+ CD25- LAP+ regulatory T cell and is associated with down-regulation of IL-17+ CD4+ ICOS+ CXCR5+ follicular helper T cells." (PMID 31557991, 2016). "There are thus more SNPs of interest in SLE with functional elements within lupus-associated LD blocks in CD19+ cells than in either CD4+ cells or neutrophils (p < 0.05)." (PMID 27906046, 2016). "We therefore tested if PP5 is overexpressed in CD4+ T cells from patients with lupus and if PP5 decreases T cell Dnmt1 expression and causes overexpression of genes normally suppressed in T cells by DNA methylation." (PMID 28239687, 2016). "It has been also observed that depletion of CD4+CD25high in lupus patients was associated with exacerbation of the disease." (PMID 27156107, 2016). "The auto-reactivity of ERK inhibitor (hydralazine)-treated CD4+ T cells was confirmed by the finding that injection into syngeneic mice caused lupus-like symptoms, similar to the 5-aza-cytidine treatments." (PMID 25988383, 2015). "Reduced basal and induced PD-1 expression was revealed on activated CD4+ T cells in SLE (systemic lupus erythematosus) patients homozygous for the PD1.3 polymorphism and reduced PD-1-mediated inhibition of early to intermediate stages of activation." (PMID 26393578, 2015). "Aberrant overexpression of miR-29b and miR-126 in lupus CD4+ T cells causes hypomethylation and overexpression of the methylation-sensitive genes CD11a and CD70, leading to T cell and B cell hyperactivity." (PMID 24991086, 2014). "Paradoxically, loss of BCMA in two different lupus-prone mouse models exacerbated disease through a CD4+ T cell-dependent mechanism that resulted in increased serum BAFF levels and autoantibody production despite reduced survival of bone marrow PCs." (PMID 25010693, 2014). "The expression of Tyro3 was strongly associated with the expression of Mer in the CD4+ T lymphocytes of lupus patients." (PMID 24650765, 2014). "MiR-142-3p has recently been identified as a down-regulated miRNA in CD4+ T cells in patients with systemic lupus erythematosus, which is associated with the over-activation of CD4+ T cells." (PMID 24743945, 2014). "Neutrophils from BCMA-deficient lupus-prone mice cultured with wild-type CD4+ T cells significantly promoted T cell proliferation and the production of IFNγ compared to neutrophils from control mice." (PMID 25010693, 2014). "Sanroque mice develop lupus-like autoimmunity that is associated with greatly increased numbers of CD4+CXCR5+ T cells and enhanced expression of IL-21." (PMID 23638156, 2013). "Based on the homology between murine and human PBX1, we investigated the expression of PBX1-d, the isoform over-expressed in the NZM210 allele, in lupus patients' CD4+ T cells." (PMID 21708033, 2011). "We have reported that the murine Sle1a.1 lupus susceptibility locus results in the production of activated and autoreactive CD4+ T cells, and in a reduction of the Treg pool." (PMID 21708033, 2011). "In addition to the B6 background, we bred Gls1 CD4-KO to the Sle1b lupus-susceptibility locus, yielding 4 groups of mice: Gls1 CD4-KO and Gls1fl/fl (“B6”) controls, and Sle1b Gls1 CD4-KO with Sle1b controls." (PMID 40956613, 2025).
lupus (continued). "It has been demonstrated that in lupus‐prone animals, the hypoxic environment linked to renal tissue damage causes CD4+ and CD8+ T lymphocytes to overexpress hypoxia‐inducible factor‐1 (HIF‐1), which leads to metabolic reprogramming, enhanced effector function and resistance to apoptosis." (PMID 40976999, 2025). "In addition to C1q deficiency, lupus is also hallmarked by an enhanced immune response in CD4+ T-cells." (PMID 40429614, 2025). "In addition, it has been reported that intracellular iron is increased in lupus patient CD4+ T cells and intracellular IO promotes pathogenic Tfh differentiation, GC B cell expansion, and autoantibody production in lupus-prone mice." (PMID 39867458, 2025). "Similarly, the low expression of CTLA4 in Foxp3+CD25+CD4+ Tregs has been negatively associated with disease activity in patients with systemic lupus erythematosus." (PMID 39284778, 2024). "Accordingly, blocking the DNA sensing pathway in CD4+ T cells by genetic knockout of Zak or using our newly developed ZAK inhibitor iZAK2 attenuated all pathogenic characteristics in a lupus-like inflammation mouse model induced with Trex1-deficient CD4+ T cells." (PMID 39872301, 2023). "Here, we showed that the overactivated DNA sensing through the KU-ZAK system in Trex1–/–CD4+ T cells greatly enhanced the glycolysis, thereby leading to sever pathogenic symptoms in an inducible lupus-like inflammation model, which is a novel mechanism for accumulated DNA in pathogenesis in SLE." (PMID 39872301, 2023). "Consistently, in vivo, administration of either iZAK2 or 2-DG could attenuate pathogenic characteristics in a lupus-like inflammation model induced with Trex1-/- CD4+ T cells." (PMID 39872301, 2023). "Moreover, MHC class II-deficient lupus-prone mice, which have significantly decreased populations of CD4+ T cells, were protected from disease development, strongly supporting a role for CD4+ T cells in disease pathogenesis." (PMID 35055071, 2022). "Finally, as also observed in the clinical clusters, we statistically confirmed the association with CD4+ T cells transcriptomic clusters and lupus severity index (p < 0.05)." (PMID 33883687, 2021). "Hypomethylation at LTR2C in lupus CD4+ T cells is associated with enhanced ERV-E expression." (PMID 34019642, 2021). "In line with findings in psoriatic disease, abnormal DNA methylation also characterizes other auto-immune/inflammatory disorders, such as systemic lupus erythematosus (SLE), where global DNA hypomethylation of CD4+ T cells has been associated with T cell autoreactivity in active lupus patients." (PMID 33869291, 2021). "However, a lower or inverted CD4+/CD8+ T cell ratio can also be linked with systemic lupus erythematosus, chronic inflammation, and cytomegalovirus infection as well." (PMID 33937149, 2021). "ncRNAs are implicated in regulating lupus CD4+ T cell over-activation." (PMID 32308657, 2020). "Therefore, we suspected that the three upregulated mRNAs with ac4C hyperacetylation in lupus CD4+ T cells were highly associated with SLE by regulating mRNA catabolic processes and translational initiation." (PMID 32984334, 2020). "However, the dysfunction of ncRNAs alters the gene expression profiles, disturbs the normal biological processes of CD4+ T cells, and leads to the functional changes of CD4+ T cells, which is an underlying cause of systemic lupus erythematosus (SLE)." (PMID 32308657, 2020). "The observation that CD4+ T cells treated with the DNA methylation inhibitor 5-azaC could cause a lupus-like disease suggested that drugs which cause lupus may be DNA methylation inhibitors." (PMID 30764520, 2019). "In addition, the suppression effect against glomerulonephritis in lupus-prone mice by nasal anti-CD3 treatment was found to be associated with a significant reduction in the percentage of IL-17 expressing CD4+ICOS+CXCR5+ T cells." (PMID 31597242, 2019).